RBSN (rabenosyn, RAB effector)
Description:
Rab4/Rab5 effector protein acting in early endocytic membrane fusion and membrane trafficking of recycling endosomes. Required for endosome fusion either homotypically or with clathrin coated vesicles. Plays a role in the lysosomal trafficking of CTSD/cathepsin D from the Golgi to lysosomes. Also promotes the recycling of transferrin directly from early endosomes to the plasma membrane. Binds phospholipid vesicles containing phosphatidylinositol 3-phosphate (PtdInsP3). Plays a role in the recycling of transferrin receptor to the plasma membrane.
Synonyms: ZFYVE20; KAREVS; MFANDO; Rabenosyn-5
Tractability: Small molecule: a structure with a bound ligand is known. Antibody: UniProt places it where antibodies can reach, with medium confidence; its Gene Ontology location is reachable by antibodies, with medium confidence. PROTAC: ubiquitination databases record sites on it; its protein half-life has been measured.
Gene: Protein-coding gene on chromosome 3 (15,068,571 to 15,099,163, reverse strand). Ensembl gene ENSG00000131381.
Subcellular location: Cell membrane; Early endosome membrane
Subcellular location (Human Protein Atlas): Vesicles
Pathways (Reactome):
Hemostasis: Factors involved in megakaryocyte development and platelet production
Immune System: Toll Like Receptor 9 (TLR9) Cascade
Gene Ontology:
Molecular function: phosphatidylinositol-3-phosphate binding; protein binding; zinc ion binding; metal ion binding; small GTPase binding
Biological process: early endosome to Golgi transport; Golgi to lysosome transport; regulation of Golgi organization; endosomal transport
Cellular component: early endosome; early endosome membrane; extracellular exosome; endosome; endosome membrane; cytosol; plasma membrane
Genetic constraint (gnomAD): Loss-of-function variants: 35 observed, 62.71 expected, observed/expected ratio (o/e) 0.56, 90% interval 0.43 to 0.74. The upper end of that interval is the gene's LOEUF score, 0.74, which puts it in group 3 of 6, group 1 being the genes least tolerant of losing a copy. Missense variants: 845 observed, 1,036.1 expected, observed/expected ratio (o/e) 0.82, 90% interval 0.77 to 0.86. Synonymous variants: 322 observed, 386.98 expected, observed/expected ratio (o/e) 0.83, 90% interval 0.76 to 0.91.
Homologues: Orthologues: chimpanzee RBSN (99% identical), macaque RBSN (98% identical), dog RBSN (90% identical), rabbit RBSN (88% identical), pig RBSN (84% identical), mouse Rbsn (84% identical), rat Rbsn (84% identical), guinea pig RBSN (78% identical), tropical clawed frog rbsn (61% identical), zebrafish rbsn (54% identical), Caenorhabditis elegans rabs-5 (20% identical), Drosophila melanogaster Rbsn-5 (20% identical).
Diseases named in the same sentence as RBSN in open-access papers:
RBSN is named in the same sentence as 9 diseases in open-access papers, as found by Europe PMC text mining. Sharing a sentence is not in itself a finding about the gene and the disease. The quoted sentences say what the papers report.
Sepsis (1 paper, 2025). Sepsis is defined as life-threatening organ dysfunction caused by a dysregulated host response to infection. "The determination of key genes, such as PRIM2, SYNPR, and RBSN, through pre-operative blood tests could enhance risk stratification, enable early detection of post-operative sepsis, and guide targeted interventions to improve patient outcomes." (PMID 41473159, 2025).
RBSN also shares sentences with these, for which no sentence is quoted: Alzheimer disease (1 paper); developmental delay (1); Epileptic encephalopathy (1); glioma (1); hepatocellular carcinoma (1); lung carcinoma (1); malaria (1); schizophrenia (1).